MTOR (mechanistic target of rapamycin kinase)
Diseases named in the same sentence as MTOR in open-access papers (continued):
Sharing a sentence is not in itself a finding about the gene and the disease.
lymphangioleiomyomatosis (51 papers, 2009 to 2025). A multifocal neoplasm with perivascular epithelioid cell differentiation affecting almost exclusively females of child-bearing age. "Everolimus, an mTOR inhibitor, is approved in many countries for the treatment of renal angiomyolipoma, lymphangioleiomyomatosis (LAM) and/or partial-onset epilepsy associated with TSC in addition to SEGA." (PMID 39165678, 2024). "In another disease also caused by activation of the mTOR signaling pathway and characterized by smooth muscle cell infiltration, lymphangioleiomyomatosis, sirolimus has shown persistent efficacy and long-term safety." (PMID 37189093, 2023). "This review will also highlight the tumor-suppressive tuberous sclerosis complex (TSC) mutated, mTOR-hyperactive lung disease of women, lymphangioleiomyomatosis (LAM)." (PMID 33668092, 2021). "Lymphangioleiomyomatosis (LAM) cells are over-proliferative smooth muscle-like cells with TSC suppressor mutations that result in excessive activity of mTOR-driven growth." (PMID 31878201, 2019). "Lymphangioleiomyomatosis is a rare disease caused by unregulated activation of mammalian target of rapamycin (mTOR) signalling pathway." (PMID 30428897, 2018). "Further, the combination of bevacizumab and temsirolimus has shown preliminary evidence of activity in other tumors in which activation of the PI3 kinase/AKT/mTOR axis has been implicated, including salivary duct tumors and lymphangioleiomyomatosis." (PMID 24742900, 2014). "Recent studies have shown that activation of mTOR in lymphangioleiomyomatosis-associated angiomyolipomas through phosphorylation of S6 protein at Ser235/236." (PMID 19265534, 2009). "Current evidence indicates that lymphangioleiomyomatosis (LAM) arises from TSC1/2 gene mutations driving constitutive activation of the mTOR signaling pathway, which promotes dysregulated proliferation of neoplastic LAM cells." (PMID 41204185, 2025). "Rapamycin (sirolimus) is already approved and successfully used in lymphangioleiomyomatosis (LAM), a progressive, cystic lung disease, associated with inappropriate activation of mTOR." (PMID 32534452, 2020). "Sirolimus, a mTOR inhibitor with antiangiogenic properties, was approved in Japan in 2015 for the treatment of lymphangioleiomyomatosis." (PMID 40748519, 2025). "The identification of mTOR hyperactivation as key to lymphangioleiomyomatosis pathogenesis has enabled the development of Sirolimus, an oral mTOR inhibitor, as an effective treatment." (PMID 40641534, 2025). "Lymphangioleiomyomatosis (LAM) is treated using an inhibitor of the mechanistic target of rapamycin mTOR inhibitor." (PMID 38698783, 2024). "The mTOR inhibitor sirolimus is prescribed to treat children with varying diseases, ranging from vascular anomalies to sporadic lymphangioleiomyomatosis to transplantation (solid organ or hematopoietic cell)." (PMID 37021042, 2023). "In 2015, sirolimus became the first drug approved by the US FDA for the treatment of lymphangioleiomyomatosis (LAM), a rare, progressive, cystic lung disease associated with inappropriate activation of mTOR signaling." (PMID 33467464, 2021). "VEGF-D has also been shown to be up-regulated by mechanistic (formerly mammalian) target of rapamycin (mTOR), a master regulator of cell growth, proliferation, and survival that has been implicated in PAH, lymphangioleiomyomatosis (LAM), and cancer." (PMID 33117832, 2020). "Lymphangioleiomyomatosis (LAM) is a rare metastatic cystic lung disease due to a mutation in a TSC tumor suppressor, resulting in hyperactive mTOR growth pathways." (PMID 31878201, 2019). "However, clinical trials of mTOR inhibitors demonstrated regression of tumours in the brain and kidney and stabilisation of lung function in those patients with lymphangioleiomyomatosis (LAM)." (PMID 40426219, 2025).
lymphangioleiomyomatosis (continued). "Furthermore, patients with TSC often have other indications for the use of mTOR inhibitors, such as large angiomyolipomas, SEGAs, lymphangioleiomyomatosis, or refractory epilepsy." (PMID 33897589, 2021). "Inhibition of mTOR is the standard of care for lymphangioleiomyomatosis (LAM)." (PMID 34378323, 2021). "Small Molecule Inhibitors: mTOR inhibitors like rapamycin indirectly suppress GPNMB in lymphangioleiomyomatosis (LAM), reducing tumor growth by 60% in murine models." (PMID 41180454, 2025). "Among lung neoplasms, sporadic lymphangioleiomyomatosis (LAM) is the only entity for which an mTOR inhibitor is approved as a first-line treatment option." (PMID 38339294, 2024). "It was also used for the treatment of patients with lymphangioleiomyomatosis (LAM), a rare, cystic lung disease resulting from inappropriate activation of mTOR." (PMID 31849609, 2019). "Lymphangioleiomyomatosis (LAM) is a rare lung disease and the mammalian target of the rapamycin (mTOR) inhibitors has been used as an effective therapy." (PMID 30107845, 2018). "Previous work has identified a role for MTOR in the lung regulating lung branching morphogenesis during normal development and in disease pathogenesis by mesenchymal cell migration in lymphangioleiomyomatosis (LAM)." (PMID 40446022, 2025). "Lymphangioleiomyomatosis (LAM) is a rare disease involving the proliferation of LAM cells in the lungs and the axial lymphatic system and mechanistic target of rapamycin (mTOR) inhibitors are the only effective medicines for treating it." (PMID 38784348, 2024). "In addition, we speculate that by down-regulating the mTOR gene, these mirnas could perhaps counteract the over-activation of the mTOR pathway that is seen in diseases such as Lymphangioleiomyomatosis (LAM) and certain cancers." (PMID 22299047, 2012). "Sirolimus, an mTOR (mammalian target of rapamycin) inhibitor, is the first FDA-approved drug for treating LAM (lymphangioleiomyomatosis)." (PMID 41204185, 2025). "The PI3K/AKT/mTOR signaling pathway is altered in several disease states such as cancer, immune system-related diseases, idiopathic pulmonary fibrosis (IPF), COPD and lymphangioleiomyomatosis (LAM)." (PMID 30774592, 2019). "mTOR, a serine/threonine protein kinase regulating cell growth and proliferation, transcription, and protein synthesis, is frequently hyperactivated in neoplastic conditions, tuberous sclerosis complexes (TSC), and lymphangioleiomyomatosis (LAM)." (PMID 24571487, 2014).
mesothelioma (51 papers, 2009 to 2025). A usually malignant and aggressive neoplasm of the mesothelium which is often associated with exposure to asbestos. "The loss of Merlin in malignant mesothelioma cells allows for an overexpression of the PI3K/Akt/mTOR pathway." (PMID 30965570, 2019). "Previous studies showed that the mTOR pathways were often activated in many of mesothelioma clinical specimens and the elevated expression was linked with poor prognosis of the patients." (PMID 28464864, 2017). "To further our understanding on the association of Cul4A and Gli1 expression in mesothelioma cells, we analysed mTOR expression after Cul4A knockdown by siRNA and mTOR expression was decreased." (PMID 26218750, 2015). "In a similar study, incubation of mesothelioma cells with different concentrations of Everolimus (20, 40, and 80 μM), an mTOR inhibitor, reduced TNT and cell projections over time." (PMID 38956646, 2024). "To date, mTOR inhibitors have been investigated, and an allosteric mTOR inhibitor, rapamycin, has been demonstrated to have selective growth inhibitory effects in NF2-deficient mesothelioma cells." (PMID 37180489, 2023). "Although phosphorylation of S6 can also be regulated by enhanced RAS/RAF/ERK/mTORC1 activity some lines of evidence support the link between pS6 and PI3K/Akt/mTOR in mesothelioma." (PMID 36115922, 2022). "As a result, targeting PI3K/AKT/mTOR reduces 70–80% of the cell viability in mesothelioma cell lines." (PMID 35501851, 2022). "Accordingly, the suppression of PI3K/mTOR by BEZ235 is suggested to have a greater anti-proliferative effect on all mesothelioma cell lines compared with other inhibitors like mTOR (RAD001) and (MEK) U0126 inhibitors." (PMID 35501851, 2022). "Our study revealed that inhibiting HSP70 by VER‐155008 disrupts the PI3K/AKT/mTOR pathway to suppress mesothelioma cell line proliferation by inducing G1 cell cycle arrest, in addition to inhibiting protein refolding which is a known function of HSP70." (PMID 33319489, 2021). "While unrelated to the PI3K/mTOR pathway, previous literature characterized NF2 and BAP1 as some of the most commonly mutated genes in patients diagnosed with mesothelioma." (PMID 33660194, 2021). "Further studies of PI3K/mTOR inhibitors for patients diagnosed with advanced mesothelioma are warranted to identify the characteristics of patients benefitting from this class of agents as well as to elucidate potential synergistic combination therapies." (PMID 33660194, 2021). "A number of studies have shown a loss of PTEN in mesothelioma and an associated overexpression of the PI3K/Akt/mTOR pathway." (PMID 30965570, 2019). "Dactolisib (BEZ235) treatment inhibited mesothelioma cell growth by targeting mTOR and similarly, treatment with the mTOR inhibitor temsirolimus stopped MPM cell proliferation and was synergistic with cisplatin treatment in vitro and in vivo." (PMID 31632972, 2019). "Eighty-five mesotheliomas were immunoreactive for mTOR, of which 29 (28.7%) showed moderate to strong reactivity." (PMID 29755689, 2018). "To assess the frequency of co-activation in primary mesotheliomas, we examined the co-expression of mTOR and ALK, ROS1, and MET at both mRNA and protein levels in tumor samples by qRT-PCR and IHC, respectively." (PMID 29755689, 2018). "Taken together, our results indicate that pirfenidone targets multiple pathways (MAPK/ERK and AKT/mTOR) involved in mesothelioma cell survival and motility." (PMID 29968778, 2018). "MLN4924 alone caused only a moderate inhibition of mesothelioma cell growth, but the combination of MLN4924 and GDC-0980, an mechanistic target of rapamycin/phosphatidylinositol 3-kinase (mTOR/PI3K) inhibitor, strongly suppressed cell proliferation." (PMID 29587439, 2018).
mesothelioma (continued). "Although in vivo experiments are lacking, in vitro data indicate that a combination treatment with the CDK4/6 inhibitor, palbociclib, and a PI3K/mTOR dual inhibitor exerts a synergistic effect on mesothelioma cell growth." (PMID 29587439, 2018). "Although the antitumor activity of the new mTOR inhibitors against mesothelioma has yet to be demonstrated, enhanced clinical benefits can be expected." (PMID 29587439, 2018). "Unfortunately, however, a phase II clinical trial of everolimus, a first-generation mTOR inhibitor rapamycin analog (so-called rapalog), demonstrated that there was insufficient activity in patients with advanced mesothelioma." (PMID 29587439, 2018). "Here, we have explored the anti-tumor effects of a simultaneous inhibition of mTOR and ALK on the growth of a patient-derived mesothelioma graft with co-activated mTOR and ALK." (PMID 29755689, 2018). "In malignant pleural mesothelioma, overexpression of Met, Akt, and mTOR have been demonstrated, and the combination of Met and dual PI3K/mTOR inhibitors showed synergistic effect in reducing mesothelioma cell lines viability and mouse xenografts growth." (PMID 30406111, 2018). "Taken together, rapamycin/crizotinib co-treatment affected aberrant cell signaling in an mTOR/ALK-positive mesothelioma graft by simultaneous blocking of mTORC1, AKT and STAT3." (PMID 29755689, 2018). "The involvement of the mTOR pathway in mesothelioma formation has been suggested in several studies." (PMID 29587439, 2018). "We next tried to evaluate the role of Cul4A on the degradation of mTOR protein in Cul4A overexpressed H28 mesothelioma cells (pBABE Cul4A), following the addition of cycloheximide." (PMID 26218750, 2015). "We have previously tested several inhibitors of the PI3K/Akt (LY294002 and wortmannin) and mTOR (rapamycin) pathways or both (PI-103), by using 3D mesothelioma models grown from cell lines (multicellular spheroids) and actual tumor (tumor fragment spheroids)." (PMID 26284517, 2015). "Here, we investigate the activity of GDC-0980, a novel dual PI3K/mTOR inhibitor, which has been proposed to be effective in mesothelioma." (PMID 26284517, 2015). "The PI3K/Akt and mTOR pathways are frequently activated in mesothelioma and have roles in its pathogenesis, survival and progression." (PMID 26284517, 2015). "In this study, we analysed mTOR protein level after Cul4A inhibition by siRNA, and our results showed that mTOR protein level was reduced faster in mesothelioma cells when Cul4A transcription was inhibited." (PMID 26218750, 2015). "Our data further establish the deregulation of the translational machinery in mesothelioma cells, suggesting that this tumor is rather peculiar in its capability to sustain translation, being insensitive to inhibition of the mTOR pathway." (PMID 26462016, 2015). "In this study, our results showed that Cul4A inhibition reduces mTOR protein expression in mesothelioma cells." (PMID 26218750, 2015). "In this study, we aimed at identifying mechanisms accounting for sensitivity versus resistance towards dual PI3K/mTOR inhibitors in a large panel of mesothelioma cell lines." (PMID 25950487, 2015). "Together, these results suggest that mTOR expression is, in part, regulated by Cul4A expression in the mesothelioma cells." (PMID 26218750, 2015). "Activation of the Akt/mTOR pathway is detected in the majority of mesothelioma cell lines and, in mouse models of mesothelioma, its inhibition has been shown to improve response to chemotherapy." (PMID 26284517, 2015). "Quantitative analysis of western blotting images showed that both Gli1 and mTOR protein levels were decreased after Cul4A knockdown in the mesothelioma cells." (PMID 26218750, 2015).
mesothelioma (continued). "The mTOR pathway is involved in ezrin- induced malignant phenotype, moreover the mTOR inhibition has shown antitumor effect in mesothelioma preclinical models." (PMID 25952930, 2015). "The PI3K/Akt/mTOR pathway plays a key role in the progression of a number of solid tumors, including mesothelioma." (PMID 25026285, 2014). "In vitro 3-D spheroid models of mesothelioma demonstrate increased resistance to drugs and apoptosis compared to 2-dimensional cultures, and this is at least in part mediated by mTOR; however, inhibitors of mTOR can overcome this acquired resistance." (PMID 25400582, 2014). "The protein kinase mammalian target of rapamycin (mTOR) is involved in the regulation of several processes, including cell proliferation, autophagy and apoptosis, and its aberrant activation in mesothelioma makes it a potential therapeutic target for this tumor." (PMID 40918456, 2025). "However, mTOR inhibitors such as everolimus had limited clinical activity in a Phase II clinical trial in an unselected mesothelioma cohort." (PMID 36138075, 2022). "Notably, the safe, modest but durable antitumor activity of the dual inhibitor of PI3K and mTOR apitolisib has already been confirmed in patients with advanced solid tumor including mesothelioma." (PMID 31752449, 2019). "It has been reported that activating the Notch1/Hes1 pathway could accelerate cell invasion, migration and proliferation through the PI3k/AKT/mTOR pathway in acute T lymphocyte leukaemia and mesothelioma." (PMID 31382985, 2019). "Considering the reports of mTORC2 activation in mesothelioma cells due to the loss of PTEN, which is an mTORC2 negative regulator, or the increased phosphorylation of mTORC2 substrate AKT, PI3K/mTOR dual inhibitors are predicted to be more effective in suppressing mesothelioma growth than rapalogs." (PMID 29587439, 2018). "Immunostaining of ALK, MET and mTOR on tissue microarrays was interpretable in 101 mesotheliomas." (PMID 29755689, 2018). "Previous studies have suggested that aberrant activation of PI3-K/AKT/mTOR signaling due to down-regulation or complete loss of PTEN or an alternative mechanism of PIK3CA mutation, is a potential therapeutic target in LPS and mesothelioma." (PMID 25888633, 2015). "Furthermore, we analysed mammalian target of rapamycin (mTOR) and Gli1 expression after Cul4A inhibition, and a potential linkage between Cul4A, mTOR and Gli1 expression in mesothelioma cells was suggested in this study." (PMID 26218750, 2015). "Increased Cul4A protein expression was detected in the Cul4A overexpressed H28 cells compared to the EV transfected control cells 7, and mTOR protein expression was significantly increased (3.5-fold) in the mesothelioma cells when Cul4A is overexpressed (*P < 0.05, t-test)." (PMID 26218750, 2015). "Notably, recent studies reported that targeting the PI3K/mTOR pathway could act as a potentially effective therapeutic strategy in mesothelioma." (PMID 37569808, 2023). "Moreover, it has also been described that TGFBI is involved in mesothelioma progression through the AKT/mTOR pathway which could be related to the HER2 pathway changes observed in TGFBI overexpression and mutagenesis." (PMID 31277676, 2019). "Moreover, our results revealed that mTOR pathway is involved in Cul4A-mediated Gli1 expression in mesothelioma cells, possibility through mTOR activation by Cul4A-mediated proteolysis of mTOR inhibitors and through crosstalk between the activated mTOR pathway and Gli1 pathway." (PMID 26218750, 2015). "Furthermore, co-inactivation of LATS2 and NF2 in mesothelioma cell lines triggers the loss of cell–cell contact inhibition, dysregulation of Hippo and mammalian target of rapamycin (mTOR) signalling, and correlates with higher sensitivity to inhibitors of the PI3K–AKT–mTOR pathway." (PMID 34226685, 2021).